GKN2 (gastrokine 2)
Synonyms: GDDR; TFIZ1; PRO813; VLTI465; blottin; BRICD1B
Tractability: Antibody: UniProt places it where antibodies can reach, with medium confidence; UniProt predicts a signal peptide or a membrane-spanning region; its Gene Ontology location is reachable by antibodies, with medium confidence.
Gene: Protein-coding gene on chromosome 2 (68,945,232 to 68,952,955, reverse strand). Ensembl gene ENSG00000183607.
Subcellular location: Secreted
Gene Ontology:
Molecular function: protein binding
Biological process: regulation of cell population proliferation
Cellular component: basal part of cell; extracellular region
Genetic constraint (gnomAD): Loss-of-function variants: 10 observed, 15.16 expected, observed/expected ratio (o/e) 0.66, 90% interval 0.41 to 1.12. The upper end of that interval is the gene's LOEUF score, 1.12, which puts it in group 4 of 6, group 1 being the genes least tolerant of losing a copy. Missense variants: 159 observed, 151.87 expected, observed/expected ratio (o/e) 1.05, 90% interval 0.92 to 1.19. Synonymous variants: 55 observed, 54.22 expected, observed/expected ratio (o/e) 1.01, 90% interval 0.82 to 1.27.
Homologues: Orthologues: chimpanzee GKN2 (97% identical), macaque GKN2 (92% identical), pig GKN2 (73% identical), rat Gkn2 (73% identical), dog GKN2 (72% identical), guinea pig GKN2 (71% identical), mouse Gkn2 (70% identical). Paralogues in human: GKN1 (25% identical), BRICD5 (18% identical).